RASGRF2 (Ras protein specific guanine nucleotide releasing factor 2)
Diseases named in the same sentence as RASGRF2 in open-access papers (continued):
Sharing a sentence is not in itself a finding about the gene and the disease.
lymphopenia (1 paper, 2009). Reduction in the number of lymphocytes. "The combined inactivation of the Rasgrf2 and Vav1 loci did not aggravate the thymocyte developmental/selection defects or the T–cell lymphopenia induced by the single Vav1 gene deficiency." (PMID 20011522, 2009).
cancer (11 papers, 2009 to 2024). A tumor composed of atypical neoplastic, often pleomorphic cells that invade other tissues. "While RASGRF2 demonstrates potent antineoplastic activity across a variety of tissues and cancers, few studies have focused on its role in STAD." (PMID 34729119, 2021). "Cancer driver genes namely CBL, GFI1, RASGRF2 and ELK3 were significantly down-regulated and associated with the significantly down-regulated lncRNAs -T216482, -T334719, -T217484 and -T265137 respectively." (PMID 31324852, 2019). "The role of RASGRF2 in the negative regulation of Cdc42 may partly explain its protective function in the context of cancer." (PMID 34729119, 2021). "As RasGRF2 and pECT2 are both RhoGEFs containing the DH domain, their activation of Rho GTPase may be independent and synergistically affect cancer progression." (PMID 33709437, 2021). "Thus, several reports have shown decreased expression and/or increased methylation of the Rasgrf2 gene in cancer cell lines and primary tumors." (PMID 20011522, 2009). "Interestingly, RASGRF2 expression is usually suppressed in various human cancers." (PMID 28686707, 2017). "The elevated expression of RASGRF2 is enriched in pathways such as the MAPK signaling pathway, cancer, Wnt signaling pathway, and others." (PMID 38656888, 2024).
tumor (8 papers, 2009 to 2025). "The present study demonstrated that high RASGRF2 expression correlates significantly and positively with gene signature-estimated Tem, macrophage, pDC, and NK cell infiltration into the tumor." (PMID 34729119, 2021). "Both STAD tissue specimens (84.7% [61/72]) and adjacent non-tumor tissue specimens (86.1% [62/72]) exhibited cytoplasmic RASGRF2." (PMID 34729119, 2021). "The diminished cellular levels of RasGRF2 in AnxA6 expressing cells and the associated decrease in the activation of Ras and ERK1/2 as well as reduced tumor growth are consistent with the inhibition of the growth of AnxA6 expressing tumor cells." (PMID 30719209, 2019). "On the other hand, high RasGRF2 expressing cells have been shown to promote cell growth but inhibit tumor cell motility." (PMID 30719209, 2019). "Flow cytometry analysis of cells obtained from the thymus, spleen and bone marrow of tumor–bearing Vav1–/–;Rasgrf2–/– and Vav1–/– animals revealed the presence of a new population characterized by the surface expression of CD3, a T–cell specific marker." (PMID 20011522, 2009). "Expression of RASGRF2 was significantly up-regulated in most TCGA dataset tumor subtypes (relative to TCGA + GTEx dataset normal tissue), including STAD (P < 0.001), and was also significantly up-regulated in TCGA dataset STAD tumor tissue (relative to adjacent non-tumor tissue) (P < 0.001)." (PMID 34729119, 2021). "However, in agreement with TCGA cohort findings, RASGRF2 staining was significantly more intense in STAD tissue specimens (score > 5 in 70.8 % (51/72)) than in adjacent non-tumor tissue specimens (score > 5 in 47.2 % (34/72)) (P = 0.0051)." (PMID 34729119, 2021). "Together these data not only support the tumor suppressor function of AnxA6 but also suggest that the effector functions of RasGRF2, cell growth via Ras activation and inhibition of cell motility via Cdc42, are important in AnxA6 modulated tumor growth and cell motility." (PMID 30719209, 2019). "Meanwhile, the stabilized RasGRF2 in these cells may be activated by other Ca2+-mobilizing oncogenic receptors to promote tumor cell growth." (PMID 30719209, 2019). "To test this we carried out GTPase activation assays to determine whether altered AnxA6 expression affected the effector functions of RasGRF2 i.e. activation of Ras proteins to promote tumor cell growth and inhibition of Cdc42 to inhibit tumor cell motility." (PMID 30719209, 2019). "To this end, we first used a standard bioinformatics comparison tool available in that database to investigate whether the expression of VAV1 and/or RASGRF2 genes was deregulated in hematopoietic tumor cells relative to their normal cell counterparts." (PMID 20011522, 2009). "Although the cellular cues that provoke down-regulation of AnxA6 in solid rumors and the role of other RasGEFs remain unknown, this study underscores the importance of AnxA6 modulated Ca2+ influx and the effector functions of RasGRF2 in AnxA6 mediated tumor growth and/or motility." (PMID 30719209, 2019). "Since Ca2+ influx is modulated by AnxA6 and RasGRF2 promotes cell growth and inhibits cell motility, our data suggest that high RasGRF2/low AnxA6 may define rapid tumor growth and poor invasiveness while low RasGRF2/high AnxA6 may be associated with invasive but slow growing tumors." (PMID 30719209, 2019). "Despite these observations, we do not consider that the putative tumor suppressor activity of RasGRF2 is a plausible explanation for the results reported here, because the Rasgrf2 deficiency only contributes to tumorigenesis when combined with the Vav1 proto–oncogene loss." (PMID 20011522, 2009). "Findings indicated that RASGRF2 transcript levels were higher in STAD relative to normal gastric tissue, as well as in STAD tumors relative to adjacent non-tumor tissue." (PMID 34729119, 2021).
tumor (continued). "This was validated at the protein level both in vitro and clinically by demonstrating that RASGRF2 protein was highly expressed in three STAD-relevant cell lines (relative to a normal gastric cell line) and in tumor relative to adjacent non-tumor tissue in an independent STAD cohort." (PMID 34729119, 2021).
adenocarcinoma (2 papers, 2021 to 2025). A common cancer characterized by the presence of malignant glandular cells. "RasGRF2 showed significantly higher expression in invasive adenocarcinomas (73/145 cases, 50%) than in non‐invasive adenocarcinomas (6/34 cases, 18%)." (PMID 33709437, 2021).
infection (2 papers, 2012 to 2016). The state of being infected such as from the introduction of a foreign agent such as serum, vaccine, antigenic substance or organism. "Several genes upstream of Ras-ERK signalling including Rasgrp1 and Rasgrf2, were expressed at higher levels in infected FoxO3a−/− macrophages, indicating that FoxO3a regulates the expression of these genes upon infection." (PMID 27599659, 2016). "We also used qRT-PCR to validate the pre-clinical over-expression of 4 of these genes previously unrecognized as playing a role in prion pathobiology; RASGRF2, TRIB1, MCL1 and HOMER1 were all confirmed to be up-regulated during the same time period post-infection in CA1 pyramidal neurons." (PMID 23144617, 2012).
neurodevelopmental disorder (1 paper, 2024). A behavioral and cognitive disorder with onset during the developmental period that involves impaired or aberrant development of intellectual, motor, or social functions. "Collectively, these findings underscore the indispensable role of RASGRF2 in neurodevelopment and synaptic processes, suggesting its significant impact on cognitive functions and potential implications in neurodevelopmental disorders." (PMID 38927744, 2024). "Supported by similar phenotype records from the Decipher database, our findings suggest that RASGRF2 abnormalities could impact essential neuronal signaling pathways, potentially leading to neurodevelopmental disorders." (PMID 38927744, 2024). "RASGRF2’s role as a mediator, linking VGCC mutations to abnormal signaling, suggests that disruptions in RASGRF2 function may contribute to neurodevelopmental disorders." (PMID 38927744, 2024).
psychiatric disorder (1 paper, 2021). A disorder characterized by behavioral and/or psychological abnormalities, often accompanied by physical symptoms. "Among the 36 duplicated genes, CMYA5, HOMER1, SERINC5 and RasGRF2 genes have been repeatedly associated with SCZ and other psychiatric disorders." (PMID 34946848, 2021).
RASGRF2 also shares sentences with these, for which no sentence is quoted: adrenocortical tumors (1 paper); alcohol addiction (1); alcoholic liver diseases (1); autoimmune disease (1); cervical cancer (1); cholangiocarcinoma (1); colorectal cancer (1); large cell neuroendocrine carcinoma of the lung (1); lymphoid tumors (1); ovarian carcinoma (1); sleep disorder (1); squamous cell carcinoma (1); Stomach Adenocarcinoma (1); thymic lymphomas (1); viral infection (1).